SRARP (steroid receptor associated and regulated protein)
Diseases named in the same sentence as SRARP in open-access papers:
SRARP is named in the same sentence as 18 diseases in open-access papers, as found by Europe PMC text mining. Sharing a sentence is not in itself a finding about the gene and the disease. The quoted sentences say what the papers report.
breast carcinoma (5 papers, 2017 to 2023). "In breast cancer cell lines, primary breast tumors, and metastatic breast cancer, SRARP has been shown to be highly co-expressed with AR." (PMID 37602329, 2023). "Other selected genes, SLC40A1, ADAMTS15, THSD4, GREB1, and SLC44A4 have been reported to be related to breast cancer, and ZG16B, FDCSP, and SRARP have been associated with other types of tumors." (PMID 32795265, 2020). "Other studies have suggested that SRARP is also involved in the transcriptional activities of ER and the activation of ER results in the suppression of SRARP expression in ER+ breast cancer cells." (PMID 29577611, 2018). "Androgen receptor and SRARP are highly co‐expressed in breast cancer and there are high levels of SRARP expression in AR+ breast cancer cell lines T‐47D and MFM‐223." (PMID 29577611, 2018). "Of note, breast cancer showed the most reduction in the SRARP promoter methylation compared to its matched normal tissue with a relative promoter methylation of 0.78‐fold (P < 0.005)." (PMID 29577611, 2018). "Collectively, these findings indicate that SRARP is highly co‐expressed with AR in breast cancer and has transcriptional regulatory effects on AR and ER signaling." (PMID 29577611, 2018). "Furthermore, functional investigations in breast cancer cells revealed an interaction between AR and SRARP." (PMID 37602329, 2023). "Furthermore, dual regulatory effects of AR on SRARP expression are consistent with the fact that these genes are highly co‐expressed in breast cancer." (PMID 29577611, 2018). "Notably, SRARP is highly co‐expressed with AR in breast cancer cell lines, primary breast tumors, and metastatic breast cancer." (PMID 29577611, 2018). "MDA‐MB‐231 (breast cancer), DU‐145 (prostate cancer), and A549 (non‐small‐cell lung cancer) cell lines were employed for colony forming assays in view of the fact that they all have low levels of SRARP and HSPB7 expression." (PMID 29577611, 2018). "Furthermore, a combination of bioinformatics analysis and biochemical studies revealed that SRARP is a phosphothreonine protein and an interacting partner of 14‐3‐3 in breast cancer cells." (PMID 29577611, 2018). "Moreover, functional studies identified an interplay between AR and SRARP in breast cancer cells." (PMID 29577611, 2018). "In contrast, AR‐ breast cancer lines MDA‐MB‐231 and MDA‐MB‐468 have low expression levels of SRARP." (PMID 29577611, 2018). "Interestingly, similar to SRARP, SPEN is also a transcriptional corepressor of nuclear hormone receptors that has a tumor suppressor function in breast cancer." (PMID 29577611, 2018). "In addition, SRARP is also repressed by ER activation, providing another layer of negative transcriptional regulation by steroid receptors in breast cancer cells." (PMID 29577611, 2018).
breast tumors (3 papers, 2017 to 2023). "SRARP also has a fairly advanced countenance in breast tumors that are estrogen receptor-positive (ER+), lower grade, and lobular histology." (PMID 37602329, 2023). "SRARP also has a relatively higher expression in breast tumors that are estrogen receptor‐positive (ER+), lower grade, and lobular histology." (PMID 29577611, 2018).
cervical cancer (1 paper, 2018). A primary or metastatic malignant neoplasm involving the cervix. "In addition, SRARP and HSPB7 showed significant copy number gains in only three cancer types, namely cervical cancer, sarcoma, and glioblastoma with gains of 0.15, 0.14, and 0.07 copies, respectively (P < 0.001)." (PMID 29577611, 2018).
endometrial cancer (1 paper, 2018). Primary or metastatic malignant neoplasm involving the endometrium (mucous membrane that lines the endometrial cavity). "In addition, there was a significant decrease in the relative promoter methylation of SRARP between 0.89‐ and 0.95‐fold in colon, liver, prostate, rectal, and endometrial cancers (P < 0.005)." (PMID 29577611, 2018).
prostate carcinoma (1 paper, 2018). A carcinoma that arises from epithelial cells of the prostate gland. "Of note, SRARP promoter methylation and gene expression inversely correlate in most tumor types, and particularly promoter hypomethylation is associated with the observed increase in SRARP expression in breast and prostate cancers." (PMID 29577611, 2018). "Comparatively, SRARP gene set in prostate cancer was highly enriched for signaling genes associated with small GTPases, MAPK pathway, protein ubiquitination, and serine phosphorylation/protein kinase activity." (PMID 29577611, 2018). "Therefore, SRARP‐co‐expressed genes in breast and prostate cancers have similar functional terms associated with transcriptional regulation, small GTPases, and chaperone proteins." (PMID 29577611, 2018). "Importantly, in breast and prostate cancers, a relative increase in SRARP expression in tumors is associated with the hypomethylation of its promoter." (PMID 29577611, 2018). "In addition, the drastic inhibition of Akt protein expression after SRARP overexpression in DU‐145 cell line may be explained by the fact that SRARP‐co‐expressed genes in prostate cancer are associated with the protein ubiquitination pathway that regulates protein degradation." (PMID 29577611, 2018). "Importantly, in breast and prostate cancer cell lines that have low SRARP levels, SRARP functions as a tumor suppressor and the overexpression of this gene markedly inhibits colony formation and cell viability." (PMID 29577611, 2018). "Therefore, SRARP expression is associated with transcriptional regulation, small GTPases, and chaperone proteins in both breast and prostate cancers; however, SRARP also correlates with unique pathways in each malignancy." (PMID 29577611, 2018).
prostate tumors (1 paper, 2018). "Of note, there is an increased expression of SRARP in breast and prostate tumors compared to their normal tissues that corresponds with its promoter hypomethylation in these cancers." (PMID 29577611, 2018).
sarcoma (1 paper, 2018). A usually aggressive malignant neoplasm of the soft tissue or bone. "In contrast, SRARP promoter methylation was significantly increased in cervical, head and neck, renal clear cell, renal papillary and thyroid cancers in addition to sarcoma and skin melanoma by 1.05‐ to 1.25‐fold (P < 0.005)." (PMID 29577611, 2018). "In contrast, SRARP differential expression showed significant negative values between −0.06 and −5.47 (P < 0.02) in head and neck, renal clear cell, renal papillary, lung squamous cell, rectal, stomach, and thyroid cancers in addition to sarcoma." (PMID 29577611, 2018).
tumor (7 papers, 2017 to 2025). "Steroid receptor-associated and regulated protein (SRARP) exerts a tumor-suppressive effect by inhibiting the epithelial–mesenchymal transition via Wnt signaling in EC." (PMID 40804837, 2025). "Of note, tumor suppressor functions of SRARP and HSPB7 are associated with the downregulation of Akt and ERK signaling in cancer cells." (PMID 29577611, 2018). "For example, SRARP (Steroid Receptor Associated And Regulated Protein) is a protein coding gene, which could function as a tumor suppressors and predict clinical outcome in malignancies." (PMID 32850325, 2020). "Therefore, an interaction with 14‐3‐3 creates another common molecular feature between HSPB7 and SRARP proteins, which may present an underlying mechanism for their function as tumor suppressors." (PMID 29577611, 2018). "SRARP (C1orf64) is a tumor suppressor that can be used to predict the clinical outcomes of malignant tumors." (PMID 34671397, 2021). "SRARP expression is inversely correlated with genes that promote cell proliferation and signal transduction, which supports its functions as a tumor suppressor." (PMID 29577611, 2018). "Of note, genome‐ and epigenome‐wide associations of SRARP and HSPB7 with survival strongly support their tumor suppressor functions." (PMID 29577611, 2018). "Tumor suppressor functions of SRARP and HSPB7 are supported by the fact that the overexpression of these genes markedly suppresses colony formation and cell viability in cancer cell lines." (PMID 29577611, 2018). "Next, promoter methylation ratios of tumor to normal for SRARP and HSPB7 genes were calculated in each tumor type and statistical significance was tested for the differences between tumor and normal samples in each dataset using a t‐test." (PMID 29577611, 2018). "Therefore, SRARP is inversely correlated with the expression of genes that promote cancer cell growth and signal transduction in support of its function as a tumor suppressor." (PMID 29577611, 2018). "In view of the integrated nature of Akt and ERK signaling, the downregulation of both these pathways may explain the potent tumor suppressor effects of SRARP and HSPB7 on these cancer cells." (PMID 29577611, 2018). "Furthermore, genome‐ and epigenome‐wide associations of SRARP and HSPB7 with survival also strongly support their function as tumor suppressors." (PMID 29577611, 2018). "In addition, SRARP predictive value in normal solid tissues indicates that the inactivation of this tumor suppressor is an early event in carcinogenesis occurring in apparently normal epithelium." (PMID 29577611, 2018). "In view of these facts, the neighboring loci of SRARP on chromosome 1p36.13 may be a hotspot region for tumor suppressor genes." (PMID 29577611, 2018). "In view of the fact that SRARP and HSPB7 are co‐expressed gene pairs with tumor suppressor functions, the possibility of similarities between the molecular features of these proteins was further investigated." (PMID 29577611, 2018). "This study suggests that SRARP and HSPB7 are gene pairs on 1p36.13 that have tumor suppressor functions and are highly regulated by gene‐level deletions and epigenetic silencing across malignancies of multiple tissue origins." (PMID 29577611, 2018). "The results of the current study strongly suggest that SRARP and HSPB7 are tumor suppressor genes located 5.2 kb apart on 1p36.13." (PMID 29577611, 2018). "These signaling effects of SRARP and HSPB7 correspond with their potent tumor suppressor functions in these two lines." (PMID 29577611, 2018). "Subsequently, the associations between the promoter methylation and expression values for SRARP and HSPB7 in eighteen tumor datasets were measured by PCC and linear regression curve estimation." (PMID 29577611, 2018). "This study reveals that SRARP and its gene pair, HSPB7, are epigenetically regulated tumor suppressors and predict clinical outcome in malignancies." (PMID 29577611, 2018).
tumor (continued). "Therefore, SRARP and HSPB7 gene expression and promoter methylation were analyzed in eighteen tumor types and their respective normal tissues using TCGA datasets as explained in methods." (PMID 29577611, 2018). "Therefore, SRARP or HSPB7 overexpression in cancer cell lines leads to a marked reduction in clonogenicity, suggesting that these proteins function as tumor suppressors." (PMID 29577611, 2018). "Importantly, SRARP and HSPB7 have tumor suppressor functions in clonogenicity and cell viability associated with the downregulation of Akt and ERK." (PMID 29577611, 2018). "The combination of epigenetic silencing and gene‐level deletions of SRARP and HSPB7 across multiple malignancies raised the question whether these genes have a tumor suppressor function." (PMID 29577611, 2018). "In summary, SRARP and HSPB7 are tumor suppressors that are commonly inactivated in malignancies." (PMID 29577611, 2018). "Therefore, the signaling pathways that are regulated in SRARP‐ and HSPB7‐mediated tumor suppression may vary based on the tissue origin of tumors." (PMID 29577611, 2018). "Median SRARP and HSPB7 expression levels were obtained for tumor and normal samples in each dataset and differential gene expression values were calculated as follows: log2 (RPKM+1)‐transformed median values of tumor ‐ log2 (RPKM+1) of normal." (PMID 29577611, 2018).
cancer (2 papers, 2018 to 2021). A tumor composed of atypical neoplastic, often pleomorphic cells that invade other tissues. "In particular, DNA hypermethylation, lower expression, somatic mutations, and lower copy numbers of SRARP are associated with worse cancer outcome." (PMID 29577611, 2018). "Of note, a higher SRARP gene expression (≥−21.41) was significantly associated with better survival in patients with cancer compared to a lower SRARP expression of −26.58 to −21.41 (P < 0.001, log‐rank test: 82.24)." (PMID 29577611, 2018). "In particular, this is evident by the fact that DNA hypermethylation, lower gene expression, somatic mutations, and lower copy numbers of SRARP are all associated with worse cancer outcome." (PMID 29577611, 2018). "In this respect, TCGA Pan‐Cancer datasets were analyzed as explained in methods to examine the association of SRARP and HSPB7 methylation, expression, and mutations with survival across malignancies of multiple tissue origins." (PMID 29577611, 2018). "This association indicates that SRARP inactivation by deletion, epigenetic silencing, or mutations may occur in a large subset of malignancies and has a detrimental effect on cancer outcome." (PMID 29577611, 2018). "Furthermore, the predictive value of SRARP somatic mutations for survival was evaluated using TCGA Pan‐Cancer data." (PMID 29577611, 2018). "Importantly, analysis of TCGA Pan‐Cancer dataset demonstrated that SRARP and HSPB7 have an average loss of −0.15 copies across a total of 12 821 malignant samples (P < 0.001)." (PMID 29577611, 2018). "Copy number correlation analysis for SRARP was carried out using the ONCOMINE database in a total of 12 767 samples across 37 cancer datasets as explained in methods." (PMID 29577611, 2018). "Next, the association of SRARP and HSPB7 methylation and expression with survival was examined in normal solid tissues derived from TCGA Pan‐Cancer datasets, which mostly constituted of histologically normal tissues adjacent to tumors." (PMID 29577611, 2018). "In this respect, SRARP expression was significantly increased in eleven cancer lines by 2.2‐ to 146‐fold (P < 0.01)." (PMID 29577611, 2018). "In contrast, baseline expression levels of SRARP were low in the remaining twelve cancer cell lines, showing −ΔCT values between −14.69 and −21.27." (PMID 29577611, 2018). "Although a minimum level of AR activity is required for baseline SRARP expression in AR+ cancer cells, higher levels of AR activity lead to another layer of SRARP regulation through AR‐mediated suppression of this gene." (PMID 29577611, 2018). "Following the induction of demethylation in cancer cell lines using 5‐aza‐dC, there was a significant increase in SRARP expression in twelve cell lines by 4.4‐ to 13 225‐fold (P < 0.01)." (PMID 29577611, 2018). "Further studies are needed to elucidate SRARP functions in the pathobiology of malignancies and to identify the translational implications of this novel cancer gene." (PMID 29577611, 2018). "Copy number correlation analysis for SRARP was carried out in a total of 12 767 samples in 37 different cancer datasets using the ONCOMINE 4.5 database." (PMID 29577611, 2018). "Importantly, SRARP gene expression strongly predicted clinical outcome in ICGC cancer patients and normal adjacent tissues using 7514 and 618 cases, respectively." (PMID 29577611, 2018). "In addition, the fact that HSPB7 and SRARP genes were hypermethylated in fourteen and twelve cancer cell lines, respectively further supports the importance of DNA methylation in the epigenetic regulation of these genes." (PMID 29577611, 2018). "Finally, the association of SRARP and HSPB7 copy numbers with survival was examined using ICGC datasets in a total of 1177 patients with cancer." (PMID 29577611, 2018). "Moreover, ICGC datasets were analyzed to further assess the association of SRARP and HSPB7 gene expression with survival in patients with cancer using donor centric data with more than 27 years of follow up." (PMID 29577611, 2018).
cancer (continued). "Expression of HSPB7 and SRARP in fourteen cancer cell lines." (PMID 29577611, 2018). "Notably, this is associated with the downregulation of Akt and ERK signaling and SRARP expression inversely correlates with genes that promote cancer cell growth and signal transduction." (PMID 29577611, 2018). "In addition, DNA hypermethylation and a lower expression of SRARP in normal adjacent tissues predict reduced survival, indicating that SRARP inactivation is an early event in cancer development." (PMID 29577611, 2018). "Collectively, these findings raise the question whether a minimum level of AR activity may be required for baseline expression of SRARP in AR+ cancer cells, while higher levels of AR activity suppress this gene." (PMID 29577611, 2018). "Therefore, SRARP or HSPB7 overexpression significantly reduces cell viability in cancer cell lines." (PMID 29577611, 2018). "In addition, AR exerts dual regulatory effects on SRARP, and although an increased AR activity suppresses SRARP transcription, a minimum level of AR activity is required to maintain baseline SRARP expression in AR+ cancer cells." (PMID 29577611, 2018). "In addition, SRARP shows DNA hypermethylation and histone deacetylation in most cancer cell lines." (PMID 29577611, 2018). "In addition, SRARP function is examined in the pathobiology of cancer." (PMID 29577611, 2018). "As expected, SRARP and HSPB7 copy numbers showed an identical predictive pattern for survival in patients with cancer." (PMID 29577611, 2018). "Collectively, these findings strongly suggest epigenetic silencing as a key factor in the regulation of SRARP and HSPB7 expression across tumors and cancer cell lines of multiple tissue origins." (PMID 29577611, 2018). "A total of fourteen cancer cell lines were treated with 5‐aza‐dC and TSA followed by the assessment of SRARP and HSPB7 expression using qRT‐PCR." (PMID 29577611, 2018). "Finally, the effect of epigenetic silencing by DNA methylation and/or histone deacetylation strongly predicts SRARP and HSPB7 expression across multiple cancer cell lines." (PMID 29577611, 2018). "Therefore, the promoter methylation levels of SRARP and HSPB7 are significantly altered in multiple cancer types compared to their matched normal tissues, showing hypermethylation in the majority of changes." (PMID 29577611, 2018). "SRARP and HSPB7 genes were next investigated in predicting cancer outcome." (PMID 29577611, 2018). "Moreover, statistical modeling using regression analysis was performed to predict SRARP and HSPB7 expression based on their epigenetic regulation data by DNA demethylation and histone deacetylation reversal in fourteen cancer cell lines." (PMID 29577611, 2018). "Therefore, comparing SRARP and HSPB7 methylation between tumors and normal adjacent tissues may underestimate their actual hypermethylation levels in cancer." (PMID 29577611, 2018).
SRARP also shares sentences with these, for which no sentence is quoted: osteosarcoma (2 papers); colorectal cancer (1); glioblastoma (1); infection (1); melanoma (1); ovarian carcinoma (1); renal carcinoma (1); skin melanoma (1); thyroid cancer (1).